EPO (erythropoietin)
Diseases named in the same sentence as EPO in open-access papers (continued):
Sharing a sentence is not in itself a finding about the gene and the disease.
anemia (continued). "Bleeding, hemolysis, nutritional deficiencies, renal dysfunction with decreased erythropoietin synthesis, tumoral infiltration of bone marrow, myelosuppression from cancer treatment are among the common causes of anemia in cancer patients." (PMID 27542823, 2016). "Again, one of the hallmarks of malignancy-associated anemia is the reduction in endogenous erythropoietin (EPO) levels with respect to the degree of anemia." (PMID 27142617, 2016). "Anemia caused by infection or inflammation is characterized by EPO hyporesponsiveness, reduced proliferation of erythroid precursors, and decreased RBC survival." (PMID 26068006, 2015). "To address this we have transfected plasmid encoding the murine EPO gene in a transgenic mouse model with chronic kidney disease and anaemia." (PMID 26046536, 2015). "Recombinant human erythropoietin (rHuEPO) therapy has been used to correct CKD associated-anemia, particularly in ESRD patients, improving their quality of life." (PMID 26712750, 2015). "A common feature during sepsis is the development of anemia that seems to be caused by iatrogenic blood loss, depression of serum iron levels and erythropoietin production, and a decreased lifespan of erythrocytes." (PMID 25947889, 2015). "In the three studies reporting anti-EPO autoantibodies in HIV associated with anemia, well-characterized anti-EPO antibody samples from patients with pure red cell aplasia were not used for validation, but rather SLE and HIV patient sera was employed." (PMID 26599070, 2015). "Recombinant erythropoietin has been used to improve anemia associated with antiviral therapy and to minimize dose reductions, which are associated with decreased rates of sustained virologic response." (PMID 26240773, 2015). "In the remnant kidney rat model of CKD-associated anemia, long-term treatment with a high rHuEPO dose is associated with development of resistance to rHuEPO therapy as a result of anti-EPO antibodies formation." (PMID 26712750, 2015). "Delaying the introduction of EPO exposes the patient to more profound anemia and a risk of premature treatment discontinuation." (PMID 26394142, 2015). "Mechanisms by which these cytokines cause anemia include dysregulation of iron homeostasis, impaired erythropoietin response to reduced hemoglobin levels, and impaired marrow response to erythropoietin." (PMID 26024473, 2015). "Recombinant human erythropoietin (rHuEPO) is widely used to correct anemia associated with Epo deficiency." (PMID 25790231, 2015). "This study aimed to elucidate the mechanisms explaining the persistence of anemia and resistance to recombinant human erythropoietin (rHuEPO) therapy in a rat model of chronic kidney disease (CKD)-associated anemia with formation of anti-rHuEPO antibodies." (PMID 26712750, 2015). "Oxidative stress has been shown to be associated with anemia through downregulation of erythropoietin synthesis, decreased red cell production, and increased erythrocyte fragility." (PMID 26045064, 2015). "The first two articles were selected by the biomedical experts to curate the association between erythropoietin and anemia, and hence they are highly related to each other." (PMID 26440794, 2015). "In spite of the increased EPO blood levels, anemia persisted and was linked to low serum iron and transferrin levels, while serum interleukin (IL)-6 and high sensitivity C-reactive protein (hs-CRP) levels showed the absence of systemic inflammation." (PMID 25867633, 2015). "Anemia occurs during pregnancy presumably due to the hemodilution caused by greater vascular volume, EPO resistance as a result of increased cytokine production during pregnancy, and high demand of red blood cell production for fetal growth." (PMID 26370296, 2015). "In the CRF rats, despite the increased EPO serum levels, anemia persisted and was linked to low serum iron and transferrin levels, while serum IL-6 and hsCRP levels showed the absence of systemic inflammation." (PMID 26712750, 2015).
anemia (continued). "Renal diseases usually cause anemia, due to an EPO deficiency originating from the renal cortex and renal tubule fibroblasts." (PMID 25574234, 2015). "Anemia, which impairs quality of life, occurs primarily due to deficiency in the production of EPO by the kidney but can be exacerbated by iron deficiency, which contributes to the shortened lifespan of erythrocytes, among other complications." (PMID 26538835, 2015). "Although iron repletion and administration EPO analogs are currently used to treat anemia, several issues have emerged, such as high cost of EPO analogs and associated resistance as well as side effects." (PMID 26610437, 2015). "The protective or aggravating influence of different hormones (EPO, hepcidin, etc.) and factors such as inflammation, acidosis, and hypoxia due to anemia or other causes should be investigated." (PMID 25849944, 2015). "The mechanisms underlying anemia in CKD patients is attributed to several factors including decreased erythropoietin (EPO) production, low iron stores, and chronic inflammation." (PMID 26268514, 2015). "Blood transfusions or erythropoietin stimulating agents (ESA) are both successful in the treatment of anaemia, but as these modalities significantly increase the risk of recurrence and even mortality, they should be given with restraint." (PMID 26123286, 2015). "Anemia in CKD patients is largely due to a deficiency in renal production of erythropoietin (EPO), although a deficiency of iron, folate or vitamin B12 can be another possible contributing factor." (PMID 26430892, 2015). "Anemia is mainly caused by insufficient kidney EPO production and a deficiency of the available iron to support ongoing erythropoiesis in CKD patients." (PMID 26430892, 2015). "The main complications of erythropoietin and 1,25-dihydroxyvitamin D (calcitriol) deficiency are in fact anemia and secondary hyperparathyroidism." (PMID 26000281, 2015). "Anemia is mainly associated with a reduced production of EPO by the failing kidneys and with disturbances in iron metabolism." (PMID 25867633, 2015). "Chronic kidney disease (CKD) is known to cause anemia mainly due to inappropriate erythropoietin (EPO) secretion, especially in patients with end-stage renal failure." (PMID 25884723, 2015). "Chronic kidney disease causes anemia due to several mechanisms, including inadequate erythropoietin production, related to tubulointerstitial fibrosis and loss, and vascular obliteration." (PMID 25710019, 2015). "Anemia is a common feature during sepsis that occurs due to iatrogenic blood loss, depression of serum iron levels and erythropoietin production, and a decreased lifespan of erythrocytes." (PMID 25947889, 2015). "Anemia likely results from a number of processes including loss of erythropoietin (EPO) production from kidney injury, as well as EPO hyporesponsiveness or resistance from inflammation and/or infection." (PMID 24691017, 2014). "In children with cancer, anemia has many causes including: chemotherapy-induced bone marrow suppression, hemolysis, blood loss, and erythropoietin deficiency induced by nephrotoxicity of chemotherapy medication." (PMID 25598955, 2014). "Anemia in CKD patients is attributed to inadequate production of erythropoietin, iron and/or folate deficiency, secondary hyperparathyroidism, chronic inflammation, and bone marrow suppression due to uremic toxins." (PMID 24505281, 2014). "Many variables are associated with anemia, such as inflammatory factors, nutritional deficiencies, renal dysfunction and inadequate erythropoietin production." (PMID 25009627, 2014). "Systemic inflammation, functional hematinic deficiencies, erythropoietin resistance, and reduced red cell survival also lead into anemia in the setting of impaired renal compensation." (PMID 25695026, 2014). "In chronic kidney disease (CKD), impaired EPO expression causes anemia, which can be treated by supplementation with recombinant human EPO (rhEPO)." (PMID 25392999, 2014).
anemia (continued). "This condition is characterized by relative deficiency of erythropoietin which is slightly greater, although still very little in relation to the degree of anemia, when compared with anemia of the same intensity observed in other etiologies." (PMID 24760213, 2014). "Growth factors, such as erythropoietin have been used to counter the anemia associated with peg-interferon and ribavirin." (PMID 25948447, 2014). "Recombinant human erythropoietin was approved in the United States in 1989 for treatment of anemia associated with chronic renal failure, and its use subsequently expanded to additional indications." (PMID 25672222, 2014). "Since EPO was first introduced into the clinic in 1989, it has been used as an effective agent to treat anemia associated with chronic renal failure and cancer for two and half decades." (PMID 24918289, 2014). "Usually, the anemia is proportional to the severity of renal dysfunction, caused due to a deficiency of erythropoietin (EPO)." (PMID 24709756, 2014). "Patients on haemodialysis dependantant on blood transfusion instead of erythropoietin to reverse anemia are at particular risk of acquiring HCV as it is easily transmissible through blood and blood product." (PMID 25883732, 2014). "Since its introduction into clinical use in 1989, recombinant human EPO (rhEPO) has become the standard therapy for anemia associated with renal failure." (PMID 25392999, 2014). "In ESRD patients, a decrease in the production of erythropoietin is the main factor contributing to anemia, but iron deficiency anemia (IDA) is also prevalent." (PMID 24505281, 2014). "The “unexplained” anemia of elderly has been linked to two putative mechanisms, namely a progressive resistance of bone marrow erythroid progenitors to erythropoietin (EPO), and a chronic subclinical pro-inflammatory state." (PMID 24795637, 2014). "Only 4 years later, the US Food and Drug Administration (FDA) approved the first commercially available recombinant human erythropoietin (rHuEPO), epoetin alfa, for the treatment of anemia associated with chronic kidney disease (CKD)." (PMID 25426117, 2014). "Anaemia is common in normal pregnancy, and pregnancy is known to cause resistance to erythropoietin." (PMID 24348579, 2013). "As rhEPO is widely used in clinical practice for the treatment of anaemia associated with various disorders including cancer, the expression of EPO and EPOR in the kidney and especially in RCC has been a cause for concern." (PMID 23305401, 2013). "Anemia which is a common condition in HD patients is mostly due to relative deficiency of EPO secretion from the diseased kidney relative to the degree of anemia." (PMID 24282790, 2013). "Cloned in 1985, recombinant human EPO (rhEPO) has been used as a treatment for anemia (mainly caused by chronic renal failure) for more than 20 years." (PMID 24348331, 2013). "Many advanced CKD patients have anemia, both associated with reduced production of erythropoietin and with iron deficiency." (PMID 24065987, 2013). "Anemia was associated with increased levels of serum erythropoietin, which indicates the hamsters respond to the anemia by producing erythropoietin." (PMID 23533629, 2013). "Anemia is a common complication in HD patients and is characterized by a relative deficiency of erythropoietin (EPO) secretion from the diseased kidney relative to the degree of anemia." (PMID 24282790, 2013). "Immediately after surgery, anemia due to inappropriately low levels of erythropoietin or iron deficiency is common." (PMID 23984326, 2013). "Theories regarding the etiology of pyelonephritis-associated anemia include overhydration at diagnosis, endotoxin mediated hemolysis, renal erythropoietin suppression, and anemia of chronic disease." (PMID 24369448, 2013). "Patients with end stage renal disease (ESRD) undergoing chronic hemodialysis (CHD) are commonly affected by anemia, which is related to erythropoietin (Epo) deficiency, blood losses, and chronic inflammation." (PMID 23433094, 2013).
anemia (continued). "Simulations were performed to analyze the impact of EPO applications on the risk of anaemia during chemotherapy." (PMID 23755260, 2013). "Anemia in end stage renal disease is attributed to impaired erythrocyte formation due to erythropoietin and iron deficiency." (PMID 24188099, 2013). "In theory, increased EPO levels, at least in patients suffering from deficient anemia, by promoting telomerase activity in erythroid progenitor cells, should support the relevance of TL maintenance." (PMID 24453794, 2013). "According to them, high serum erythropoietin levels were associated with low maternal hemoglobin levels and suggested that maternal anemia rather induces fetal erythropoiesis." (PMID 24007344, 2013). "Erythropoietin is synthesized predominantly in the peritubular endothelium cells of the kidney and during anaemia, caused by either reduced iron intake or blood loss, the healthy kidney can increase erythropoietin production by at least 10-fold." (PMID 24064572, 2013). "Existing anemia is aggravated by underlying inflammation, which leads to alterations in iron homeostasis, impaired erythrocyte proliferation, blunted erythropoietin response, and decreased erythrocyte half-life." (PMID 22400108, 2012). "In animal studies, mice with a green fluorescent protein transgene driven by EPO regulatory sequences confirm EPO production in the ganglion cell layer in the developing retina coincident with newborn-associated anemia." (PMID 22567318, 2012). "It is noteworthy that clinical trials using EPO to treat disease associated anemia to achieve a high hemoglobin level have demonstrated adverse effects associated with EPO therapy." (PMID 22567318, 2012). "Recombinant human erythropoietin and its protein variants are used clinically for the correction of anemia secondary to CKD." (PMID 22188389, 2012). "There has been tremendous interest in anemia as a risk factor for CVD because it is potentially modifiable with iron therapy or erythropoietin." (PMID 22906142, 2012). "Generally, GD anemia resembles anemia of chronic disease in many aspects including red cell morphology, iron status, erythropoietin levels, and association with markers of inflammation." (PMID 22132347, 2012). "The etiopathology of chronic kidney disease (CKD)-associated anemia is related to inadequate generation of erythropoietin by the diseased kidney." (PMID 22188389, 2012). "In France, EPO is used in the treatment of anaemia linked to renal failure, and occasionally preoperatively in anaemic patients." (PMID 23013647, 2012). "Premature neonates are at risk for severe anemia and erythropoietin is the most important hormone in erythropoiesis." (PMID 22737576, 2012). "Anaemia in diabetes has been attributed to erythropoietin (EPO) deficiency subsequent to renal complications." (PMID 22876293, 2012). "Unexplained anemia was associated with reduced kidney EPO response, low levels of pro-inflammatory markers, and low lymphocyte counts." (PMID 23091709, 2012). "Another well studied cause of anemia in adults is the presence of antibodies to endogenous erythropoietin." (PMID 23114115, 2012). "Erythropoietin (EPO) is well demonstrated to improve anaemia associated with chemotherapy in solid tumours and quality of life in anaemic patients with cancer." (PMID 22950685, 2012). "Human recombinant EPO has been used clinically for more than 2 decades to treat anemia associated with conditions such as chronic kidney disease, antiviral HIV therapy, and cancer patients on chemotherapy." (PMID 22567318, 2012). "Any damage to kidney tissues abolishes the EPO secretion from kidney thus causing anemia in renal patients." (PMID 22040235, 2011). "Shortened red blood cells survival, decreased erythropoietin secretion by kidney, and concurrent deficiencies of iron, pyridoxine and folate have been reported to contribute to anemia." (PMID 21600038, 2011).
anemia (continued). "Previous reports denoted that administering erythropoietin can improve anaemia caused by peginterferon and ribavirin therapy and is more effective than dose reduction at improving quality of life during treatment." (PMID 21994862, 2011). "The pathophysiological process causing the anaemia being reduced erythropoietin production secondary to renal dysfunction." (PMID 22548027, 2011). "Further characterization revealed the anemia to be associated with a 2.5-fold increase in serum EPO levels and a significant decrease in absolute reticulocyte counts." (PMID 21887333, 2011). "Attempts to directly address CKD-associated anemia through treatment with recombinant EPO have generated mixed results, leading to efforts to develop gene and cell therapy based approaches for the targeted delivery of EPO in a physiologically relevant manner." (PMID 21957910, 2011). "Deficiency of EPO is known to cause anemia in chronically infected renal patients and they require regular blood transfusion." (PMID 22040235, 2011). "Management of HIV-associated anemia in high-income countries includes erythropoietin treatment, which has been associated with recovery from anemia and improved survival, but high costs restrict its use in resource-limited settings." (PMID 21745396, 2011). "Anaemia in End Stage Renal Failure (ESRF) is mainly due to loss of the endocrine function of the kidneys that lead to deficiency of erythropoietin (EPO) and development of anaemia." (PMID 21827693, 2011). "Until recently, anemia of chronic kidney disease (CKD) was thought to be primarily due to the deficiency of erythropoietin." (PMID 20066043, 2010). "A hepcidin transgenic mouse model replicates many of the pathogenic features of AI, including a mild, hypochromic anemia, sequestration of iron in the spleen, and impaired marrow response to erythropoietin." (PMID 20368776, 2010). "In cases of anemia associated with ineffective erythropoiesis, imbalance between erythrocyte supply and demand persists despite increased tissue hypoxia and increased erythropoietin." (PMID 20467559, 2010). "Deficiencies of erythropoietin and iron play a role in genesis of the anemia of Chronic Kidney Disease (CKD) and End Stage Renal Disease (ESRD) patients treated by hemodialysis (HD)." (PMID 19245700, 2009). "Mice deficient for EPO or EPO receptor (EPOR) genes die at embryonic day 13 (E13) because of severe anemia caused by deficiency in definitive erythropoiesis." (PMID 20142991, 2009). "The treatment of anaemia associated with kidney disease has been successfully carried out on more than a million patients by the use of recombinant human erythropoietin proteins." (PMID 19143750, 2009). "In animal models, EP has been shown to increase the efficiency of erythropoietin (Epo) gene transfer for the treatment of CRF-associated anemia." (PMID 19149896, 2009). "Anaemia in patients with chronic renal failure, which is caused primarily by an inadequate production of erythropoietin by the damaged kidneys, results in a reduction in length and quality of the patient's life." (PMID 19143750, 2009). "Inhibition of systemic EPO production has been clinically observed in early diabetic nephropathy and results in anemia that is associated with an aggravated course of DR." (PMID 19930719, 2009). "The main cause of anaemia in patients with CKD is insufficient synthesis of erythropoietin by the damaged kidney." (PMID 19243619, 2009). "On the contrary, recovery from anemia after erythropoietin treatment has been associated with improved survival, but high costs limit its use in poor countries." (PMID 18430196, 2008). "Recombinant erythropoietin (rhEpo) injections are commonly used to treat anaemia linked to cancer treatment or chronic renal failure." (PMID 18334017, 2008). "Erythropoietin (with or without G-CFS) is recommended for low risk MDS patients with transfusion-dependent anaemia in whom endogenous erythropoietin levels and the transfusion-frequency are low." (PMID 18218040, 2008).